FGG (fibrinogen gamma chain)
Description:
Together with fibrinogen alpha (FGA) and fibrinogen beta (FGB), polymerizes to form an insoluble fibrin matrix. Has a major function in hemostasis as one of the primary components of blood clots. In addition, functions during the early stages of wound repair to stabilize the lesion and guide cell migration during re-epithelialization. Was originally thought to be essential for platelet aggregation, based on in vitro studies using anticoagulated blood. However, subsequent studies have shown that it is not absolutely required for thrombus formation in vivo. Enhances expression of SELP in activated platelets via an ITGB3-dependent pathway. Maternal fibrinogen is essential for successful pregnancy. Fibrin deposition is also associated with infection, where it protects against IFNG-mediated hemorrhage. May also facilitate the antibacterial immune response via both innate and T-cell mediated pathways.
Tractability: Small molecule: a structure with a bound ligand is known; it has a high-quality binding pocket. Antibody: UniProt places it where antibodies can reach, with high confidence; its Gene Ontology location is reachable by antibodies, with high confidence; UniProt predicts a signal peptide or a membrane-spanning region. PROTAC: its protein half-life has been measured. Other modalities: an approved drug acts on it.
Gene: Protein-coding gene on chromosome 4 (154,604,134 to 154,612,967, reverse strand). Ensembl gene ENSG00000171557.
Subcellular location: Secreted
Subcellular location (Human Protein Atlas): Endoplasmic reticulum; Vesicles; Predicted to be secreted
Pathways (Reactome):
Disease: Aggregated β-amyloid interacts with fibrinogen; IRAK4 deficiency (TLR2/4); MyD88 deficiency (TLR2/4); Paradoxical activation of RAF signaling by kinase inactive BRAF; Signaling by BRAF and RAF1 fusions; Signaling by RAF1 mutants; Signaling by high-kinase activity BRAF mutants; Signaling by moderate kinase activity BRAF mutants; Signaling downstream of RAS mutants
Signal Transduction: GRB2:SOS provides linkage to MAPK signaling for Integrins; Integrin signaling; MAP2K and MAPK activation; p130Cas linkage to MAPK signaling for integrins
Immune System: ER-Phagosome pathway; MyD88:MAL(TIRAP) cascade initiated on plasma membrane; Regulation of TLR by endogenous ligand
Hemostasis: Fibrin formation; Platelet degranulation
Metabolism of proteins: Post-translational protein phosphorylation; Regulation of Insulin-like Growth Factor (IGF) transport and uptake by Insulin-like Growth Factor Binding Proteins (IGFBPs)
Extracellular matrix organization: Integrin cell surface interactions
Gene Ontology:
Molecular function: cell adhesion molecule binding; extracellular matrix structural constituent; protein binding; signaling receptor binding; structural molecule activity
Biological process: blood coagulation, fibrin clot formation; cell-matrix adhesion; fibrinolysis; negative regulation of endothelial cell apoptotic process; negative regulation of extrinsic apoptotic signaling pathway via death domain receptors; plasminogen activation; platelet aggregation; positive regulation of ERK1 and ERK2 cascade; positive regulation of exocytosis; positive regulation of heterotypic cell-cell adhesion; positive regulation of peptide hormone secretion; positive regulation of protein secretion; positive regulation of vasoconstriction; protein polymerization; protein secretion; protein-containing complex assembly; response to calcium ion; positive regulation of substrate adhesion-dependent cell spreading; blood coagulation; platelet activation
Cellular component: blood microparticle; cell surface; external side of plasma membrane; extracellular exosome; extracellular matrix; extracellular region; fibrinogen complex; platelet alpha granule; endoplasmic reticulum lumen; non-collagenous component of interstitial matrix; plasma membrane; platelet alpha granule lumen
Genetic constraint (gnomAD): Loss-of-function variants: 19 observed, 50.25 expected, observed/expected ratio (o/e) 0.38, 90% interval 0.26 to 0.56. The upper end of that interval is the gene's LOEUF score, 0.56, which puts it in group 2 of 6, group 1 being the genes least tolerant of losing a copy. Missense variants: 429 observed, 524.12 expected, observed/expected ratio (o/e) 0.82, 90% interval 0.75 to 0.89. Synonymous variants: 174 observed, 183.82 expected, observed/expected ratio (o/e) 0.95, 90% interval 0.84 to 1.07.
Gene-disease validity (ClinGen):
ClinGen rates the evidence that FGG causes each of these diseases.
congenital fibrinogen deficiency (semidominant): Definitive. Congenital deficiencies of fibrinogen are coagulation disorders characterized by bleeding symptoms ranging from mild to severe resulting from reduced quantity and/or quality of circulating fibrinogen.
Homologues: Orthologues: chimpanzee FGG (99% identical), macaque FGG (92% identical), dog FGG (83% identical), rat Fgg (81% identical), mouse Fgg (81% identical), guinea pig FGG (80% identical), pig FGG (80% identical), rabbit FGG (76% identical), tropical clawed frog fgg (63% identical), zebrafish fgg (54% identical). Paralogues in human: FGB (27% identical), ANGPTL1 (27% identical), ANGPTL2 (25% identical), ANGPT1 (24% identical), ANGPTL6 (24% identical), TNR (24% identical), ANGPTL3 (24% identical), FGL1 (24% identical), FIBCD1 (24% identical), ANGPTL4 (23% identical), ANGPT4 (23% identical), ANGPTL5 (23% identical), and 13 more.
Diseases named in the same sentence as FGG in open-access papers:
FGG is named in the same sentence as 113 diseases in open-access papers, as found by Europe PMC text mining. Sharing a sentence is not in itself a finding about the gene and the disease. The quoted sentences say what the papers report.
liver cancer (11 papers, 2013 to 2025). An epithelial or non-epithelial malignant neoplasm that arises from the liver. "Furthermore, the levels of FGB and FGG in exosomes have shown promise as early diagnostic markers for colorectal cancer and liver cancer." (PMID 37953280, 2023). "Dysregulation of FGG expression has been reported in multiple malignancies, including liver cancer, stomach cancer, and prostate cancer, suggesting its potential as a tumor-associated biomarker." (PMID 40868977, 2025). "It’s noteworthy that ICAM-1 and FGG expression is correlated with favorable prognostic in particular malignant tumors such as breast and liver cancer, suggesting diverse roles of ICAM-1–FGG signaling in different malignant cell development." (PMID 39168965, 2024). "Dysregulation of FGG has also been reported in many malignant tumor types, such as liver cancer, stomach cancer, and prostate cancer, underscoring its potential relevance as a tumor marker." (PMID 37841237, 2023). "FGG is expressed in primary liver cancer tissues, and clinicopathological analyses have shown that the upregulation of intracellular FGG expression is correlated with an increase in tumor vascular infiltration." (PMID 36300097, 2022). "RT-PCR analysis showed that the expression level of FGG mRNA was significantly increased in adjacent tissues of liver cancer tissues, especially in liver cancer metastases." (PMID 31467879, 2019). "Thus, FGA, FGB, FGG and FGL1 could be important direct target genes of FOXA1 that are involved in EMT of lung and liver cancer specifically." (PMID 24093963, 2013).
COVID-19 (10 papers, 2020 to 2025). A disease caused by infection with severe acute respiratory syndrome coronavirus 2. "Following infection with a pseudotyped SARS-CoV-2 virus and live SARS-CoV-2, RNA-Seq and qPCR analyses revealed significant upregulation of fibrinogen genes (FGA, FGG), which are associated with severe COVID-19." (PMID 41453867, 2025). "Our data also showed increased levels of fibrinogen alpha, beta, and gamma chains (FGA, FGB, and FGG) in PLWH with COVID-19 compared to those in HCs." (PMID 40568587, 2025). "In the protein combination, 4 proteins including F11, F9, FGA and FGG are involved in the blood coagulation cascade, and all of them were higher expressed in COVID-19-children than those in healthy children or COVID-19-adults." (PMID 34335977, 2021). "The validation study using MRM could specifically detect AGT, FGG, APOB, SERPING1, and SERPINA3 host peptides in COVID-19 severe patients." (PMID 33995121, 2021). "In our results, F11, F9, FGG, FGA, SERPINA5, SERPINC1, and SERPINF2 are involved in the coagulation cascade, and significantly higher expressed in COVID-19-children compared with COVID-19-adults." (PMID 34335977, 2021). "Similarly, in previous reports, FGB, FGG, complements C4, C3, C5, C2, C9, and complement C1q subcomponent subunits A, B, and C (C1QA, C1QB and C1QC) were found to be upregulated in the lung tissues of patient with COVID-19." (PMID 38882332, 2024). "Further, the deep plasma proteome study of non-severe versus severe COVID-19 patients revealed only 38 differentially expressed proteins, out of which proteins such as FGG, S100A8, VWF, SAA4, SERPIND1, and SERPINA6 were identified to be significantly upregulated in the COVID-19 severe patients." (PMID 33995121, 2021).
hepatocellular carcinoma (10 papers, 2018 to 2025). A malignant tumor that arises from hepatocytes. "Regarding the products of fibrinogen degradation, FGA influences tumor cell proliferation and survival, and high FGG levels are found in late-stage liver carcinoma, which is associated with lymph node invasion, tumor relapse, and patients’ short overall survival." (PMID 39201614, 2024). "FGG has been identified and characterized as a potential prognostic gene for predicting overall survival in hepatocellular carcinoma (HCC) patients, which enhances HCC cell migration and invasion by activating EMT." (PMID 41200166, 2025). "In addition, FGG was found to promote hepatocellular carcinoma cell migration and invasion and, thus, has been validated as a prognostic biomarker for prostate cancer and gastric cancer." (PMID 37124494, 2023). "The abnormal expression of FGG was also reported in hepatocellular carcinoma and ovarian cancer." (PMID 31998645, 2019). "FGG regulates the expression of SLUG and ZEB1, and promotes the migration and invasion of hepatocellular carcinoma cells through EMT signal pathway." (PMID 38750571, 2024). "In HCC, FGB functions in portal vein tumor thrombus formation, FGG activating epithelial to mesenchymal transition to promote migration and invasion in hepatocellular carcinoma cells." (PMID 39600945, 2024). "FGG was significantly up-regulated at the mRNA level in hepatocellular carcinoma (HCC) compared to non-cancerous adjacent tissues and may serve as a useful predictor of clinical progression of HCC patients." (PMID 30733650, 2019).
Hypofibrinogenemia (10 papers, 2016 to 2025). Decreased concentration of fibrinogen in the blood. "The authors describe a three-generation family-four members with hypofibrinogenemia caused by a novel pathogenic variant in the FGG gene (c.668G > C, p.Arg223Thr)." (PMID 40264159, 2025). "Most cases of hereditary hypofibrinogenemia result from heterozygous missense mutations of FGG, a gene associated with hepatic storage." (PMID 41245011, 2025). "His family history was significant for paternal Marfan syndrome and maternal congenital hypofibrinogenemia confirmed by finding a pathogenic variant in the FGG gene (c." (PMID 41245011, 2025). "In conclusion, our study identified a novel mutation (c.668G > C, p.Arg223Thr) in the FGG gene that causes hypofibrinogenemia, expanding the genetic spectrum and contributing to prenatal diagnosis of congenital fibrinogen disorders." (PMID 38374144, 2024). "In this study, we collected a family with hypofibrinogenemia, and genetics analysis identify a novel pathogenic variants (c.668G > C, p.Arg223Thr) in the FGG gene." (PMID 38374144, 2024). "Hypofibrinogenemia caused by mutations in the FGG gene is a rare condition associated with liver disease, caused by the accumulation of mutant fibrinogens within liver cells." (PMID 39199213, 2024). "Most fibrinogen variants in hypofibrinogenemia are localized in the FGG gene, and only 26.6% of causative mutations are localized in the FGB gene." (PMID 33322159, 2020). "With these premises, we hence checked the GnomAD for worldwide frequencies of the eight HHHS-causing mutations in the FGG gene, with the hope to determine the overall prevalence rate of this particular type of hypofibrinogenemia." (PMID 33105716, 2020). "Mutations in any of the Fibrinogen gene (FGA, FGB, FGG) can result in hypofibrinogenemia." (PMID 34071368, 2021). "When mutation in the fibrinogen gamma chain gene (FGG) results not only in hypofibrinogenemia but also in accumulation of fibrinogen within endoplasmic reticulum (ER) of hepatocytes and varying degrees of liver disease, fibrinogen storage disease (FSD) can be diagnosed." (PMID 27520927, 2016). "FGA or FGG KO in mice leads to precluded assembly of functional circulating FG protein, resulting in congenital hypofibrinogenemia and afibrinogenemia as well as related atherosclerosis, colitis, multiple sclerosis and pregnancy failure." (PMID 39168965, 2024). "We have sequenced all exons of the FGA, FGB, and FGG genes using the DNA isolated from the peripheral blood in two unrelated probands with mild hypofibrinogenemia." (PMID 33322159, 2020). "Hypofibrinogenemia can be considered the phenotypic expression of heterozygous loss of function mutations occurring within one of the three fibrinogen genes (FGA, FGB, and FGG)." (PMID 33322159, 2020).
thrombosis (8 papers, 2013 to 2026). "For instance, the p.Arg554Cys mutations in the FGA gene, the p.Ala68Thr mutation in the FGB gene, and the p.Asp364Val mutation in the FGG gene have all been linked to thrombosis." (PMID 41030265, 2025). "This TATCT allele is also relatively common (0.22 and 0.50 in HapMap European-Americans and Asians, respectively), alters the fibrinogen γ’/γA ratio by regulating the alternative polyadenylation of FGG mRNA, and is associated with an increased risk of deep vein thrombosis." (PMID 24098465, 2013). "Among 5 variants previously reported in patients with thrombosis, FGA p.Arg35Cys, FGG p.Arg301Cys, and FGG p.Asp344Gly showed markedly prolonged T lysis compared with the normal reference range, indicating altered clot formation-lysis kinetics." (PMID 42027313, 2026). "Coagulation-related factors, such as F2, SERPIND1, SERPINF2, SERPINA3, FGA, FGB, and FGG, are also downregulated, leading to coagulation dysfunction in the body, which is not conducive to post-exercise recovery and can even lead to thrombosis in severe cases." (PMID 40646880, 2025). "Genomic DNA was extracted and was genotyped for the 5-SNPs Genetic risk score (GRS), previously validated for first venous thrombosis (FVL rs6025, PTM rs1799963, ABO rs8176719, FGG rs2066865 and FXI rs2036914)." (PMID 34200207, 2021). "The aim of our present study was to determine the frequencies of thrombosis related ABO, F5, MTHFR, and FGG gene polymorphisms in morbidly obese patients and compare them with the group of nonobese individuals." (PMID 27999448, 2016).
dysfibrinogenemia (7 papers, 2015 to 2025). "The 401st arginine of the FGG gene is highly conserved, and variants at this site are known to be associated with congenital dysfibrinogenemia." (PMID 41030265, 2025). "Mutations in the genes encoding these chains—FGA, FGB, and FGG—responsible for CD have been strongly associated with the development of dysfibrinogenemia; however, the precise mechanisms of pathogenesis remain largely unclear." (PMID 41030265, 2025). "Concerning fibrinogen abnormalities, most of our patients were carriers of the frequent mutations in FGA exon 2 (p.Arg35Cys and p.Arg35His) or in FGG exon 8 (p.Arg301His), which are responsible for more than 80% of all variants in dysfibrinogenemia." (PMID 33807613, 2021). "Dysfibrinogenemia is usually associated with AD inheritance with two hotspots described, namely FGA p.Arg35 and FGG p.Arg301." (PMID 33807613, 2021). "Laboratories, where performance of TT and RT is not part of routine coagulation screening, may misdiagnose certain types of fibrinogen abnormalities, like the dysfibrinogenemia caused by FGA p.Arg35Cys/His and p.Arg38Ser mutations, or the FGG p.Arg301His mutation." (PMID 33807613, 2021).
prostate carcinoma (7 papers, 2006 to 2025). A carcinoma that arises from epithelial cells of the prostate gland. "Serum FGG levels are associated with prostate cancer and depressed patients." (PMID 39076904, 2022). "Elevated FGG is related to gastric cancer, and plasma FGG levels have been proposed as predictors of prostate cancer progression." (PMID 40868977, 2025). "Another study showed that serum FGG levels predicted the progression of prostate cancer." (PMID 37841237, 2023). "A proteomic analysis of the urine revealed APPs (FGA, FGG, HP, ITI4, SERPINA1) as biomarkers for prostate cancer, but the paper lacks the analysis of their pathophysiological role." (PMID 35328392, 2022).
afibrinogenemia (6 papers, 2017 to 2024). "One of these regions was in chromosome 4 and included FGG, the gene reported to cause fibrinogen deficiency and related to the phenotype of the proband." (PMID 29769041, 2018). "In individuals with afibrinogenemia, while most of “null allele” variants are found within FGA, missense variants usually involve amino-acid residues of fibrinogen gamma chain." (PMID 29844251, 2018). "Notably, none of these variants was annotated as pathogenic/likely pathogenic in ClinVar, while one was annotated as “DM” in HGMD, a missense variant in FGG (rs202132393; c.124G>A: p.Gly42Ser) reported in HGMD to cause congenital afibrinogenemia." (PMID 38584274, 2024). "Thus, impaired secretion of fibrinogen was suggested to cause afibrinogenemia in these reported homozygous mutant FGB- and FGG-cases." (PMID 34356081, 2021). "Furthermore, in FGG intron 6, the same research group described the only deep intronic variant (IVS6-320A→T) associated with afibrinogenemia." (PMID 29844251, 2018). "Autosomal-recessive fibrinogen deficiency appears to be virtually absent in Ashkenazi Jews (no mutations found in FGA and FGB; prevalence for FGG of 1.64 per 106 individuals), whereas, non-Finnish Europeans have a predicted exceptional rate of 23.05 per 106 individuals for the sole FGG gene." (PMID 29240685, 2017).
bleeding disorders (4 papers, 2014 to 2025). "Mutations in three genes (FGA, FGB, FGG) encoding fibrinogen α-, β- and γ-chains lead to congenital fibrinogen deficiency, which is an extremely rare hereditary bleeding disorder, affecting 1 in 1,000,000 individuals." (PMID 25275492, 2014). "Among bleeding disorders, mutations were primarily found in VWF (15%), FGG (15%), F8 (12%), F7 (12%), and FGA (11%)." (PMID 40488813, 2025). "Congenital fibrinogen disorders (CFDs) are rare bleeding disorders (RBDs) caused by mutations in 1 of the 3 fibrinogen genes (FGA, FGB, and FGG)." (PMID 38953055, 2024). "Congenital fibrinogen deficiencies are rare bleeding disorders, characterized by extensive genetic heterogeneity in all the three genes: FGA, FGB, and FGG (enconding the Aα, Bβ, and γ chain, respectively)." (PMID 32610551, 2020).
ischemic stroke (4 papers, 2019 to 2023). A stroke disorder caused by obstruction of blood flow to the brain, due to thrombotic (local blood clot formation) or embolic (due to a blood clot or other material traveling from another site) event. "AHSG is associated with alopecia-mental retardation syndrome 1, patients of familial amyloid polyneuropathy (FAP) carrying TTR Met30 mutation, and fibrinogen gamma chain (FGG) appear to be protected after ischemic stroke." (PMID 34168538, 2021). "Fibrinogen gamma chain (FGG) was diagnosed with progression of ischemic stroke, but this gene may be identified with development of CAD." (PMID 31881747, 2019). "C1QA, FGG, FN1, and VWF could therefore be involved in atherogenesis progression in patients with CSC ischaemic stroke." (PMID 34356850, 2021).